IL6 (interleukin 6)
Diseases named in the same sentence as IL6 in open-access papers (continued):
Sharing a sentence is not in itself a finding about the gene and the disease.
infection (continued). "This requires careful consideration of the administration of JAK inhibitors (or TYK2 inhibitors) in the context of inhibiting IL-6-mediated inflammatory responses, as the IFN-I responses are not supposed to be suppressed due to their positive roles in early infection." (PMID 34001144, 2021). "Data show that the IL-6 immuno-reactivity per cell at 17 h post-infection was not significantly altered by SARS-CoV-2 pseudovirus infection (11.92 ± 1.23 a.u.)or by treatment with Aβ1-42 alone (6.12 ± 1.11 a.u.)compared to the control (8.56 ± 0.66 a.u.)." (PMID 34360989, 2021). "In the G5 group, only the cytokines IL-6 and IL-17 were present from point 0, not related to infection but to the activation of the antigen itself, this group presented 100% animal mortality." (PMID 34843474, 2021). "IL-6 and TNF-α share of the ability to clear G. duodenalis in mouse infection models." (PMID 34238339, 2021). "Reticular fibroblasts located near T cells around the infection site can transmit long-lasting activation signals to CD8+T cells by upregulating ICOS ligand (ICOSL), CD40, and interleukin-6 (IL-6), which promotes the preferential differentiation of T cells into TRM cells." (PMID 34707601, 2021). "It was also shown that the production of KC, IL-10, IL-6, TNF-α, and IL-1β was significantly enhanced when bacterial loads were also significantly increased after S. pneumoniae infection at 7 days after H9N2 virus (A/Duck/Hong Kong/702/1979) infection." (PMID 33722928, 2021). "TLRs, PPRs, IL6, TREM1, and NF-κB CPs were highly activated at 24 h compared to 2 h post-infection." (PMID 33382951, 2021). "The present study has found that the postoperative serum levels of IL-6 was significantly lower in patients with urosepsis of the EXP group in comparison with those in the CON group, which represented an alleviated severity of infection and inflammation." (PMID 33411151, 2021). "Strikingly, infection with NTSNΔinlF triggered significantly higher production of cytokines IL-6 (p <0.05) and IL-1β (p <0.05) in the spleen; there was no obvious difference in TNF-α elicited by three Lm strains (p >0.05)." (PMID 35223532, 2021). "Moreover, virus mixed infection enhanced the mRNA expressions of TNF-α, IL-1β, IL-6, IL-10, IFN-α, and IFN-β by 2–170 times." (PMID 33827620, 2021). "In contrast, IL-6 is not essential for induced hydrosalpinx at a high dose of C. muridarum, but is required for exacerbating infection-induced hydrosalpinx with low dose of C. muridarum." (PMID 34093528, 2021). "Interestingly, IL-8 secretion by infected macrophages significantly increased at 24 hours after infection and further increased at 28 hours after infection, whereas IL-6 and TNF-α gradually increased at 2–28 hours after infection." (PMID 33680221, 2021). "Additionally, IL-6 was shown to be important for the generation of Tfh CD4+ T cells (through upregulation of Bcl6) and B cell responses later during LCMV Cl 13 infection." (PMID 34696381, 2021). "In this study, we found that vaccination-trained immune response produces heightened TNF-α, but not IL-6 and IL-1β, when encountered with the infection." (PMID 34544549, 2021). "We next documented that the TRIF-dependent IL-6 response was not an oddity of infection by strain 130b by infecting the TRIF KD cells with another clinical isolate of L. pneumophila, strain Philadelphia-1." (PMID 34280250, 2021). "Optimisation of Pa infection of BEAS-2B cells identified that a bacterial concentration of 2.5 x 107 PFU/ml significantly induced IL-6 release with little cell death and an incubation period of four hours was optimal for both IL-6 and CXCL8 measurement." (PMID 33524056, 2021). "For these assays, we monitored levels of TNFα, since the murine macrophages did not significantly produce IL-6 after infection with L. pneumophila." (PMID 34280250, 2021).
infection (continued). "After the infection with GTP viruses (GTPV) and PPR viruses (PPRV), cytokines such as TNF-α, IL-1β, IL-6, IL-10, IFN-α, and IFN-β might regulate their replication in vitro." (PMID 33827620, 2021). "Furthermore, the top six DEGs, including CSF3, CCL2, CCL7, IL6, CXCL11, and CXCL10, were all upregulated after infection at P3." (PMID 34026883, 2021). "As expected, infection of macrophages with WT or Δrgg2 GAS grown in CDM resulted in macrophage stimulation, as indicated by activation of NF-κB and production of large amounts of tumor necrosis factor alpha (TNF-α) and interleukin 6 (IL-6)." (PMID 33947757, 2021). "We reported here that the serum levels of TNF-α, IL-6, IL-28B, IMA and PAPP-A changed during SARS-CoV-2 infection whereas cTnT and NT-proBNP were not significantly different between the early phase and the active phase of infection." (PMID 34884175, 2021). "The PPRs, IL6, and TREM1 CPs were highly induced at 24 h compared to 2 h post-infection." (PMID 33382951, 2021). "Notably, the levels of IL-6 in WT mouse spleens were significantly higher than those in the spleens of RBP-J CKO mice at 3 and 6 h post-infection." (PMID 34040603, 2021). "Notably, throughout the 24-h course of M28ΔtatA infection, the expression trends of the TNF-α, IL-6 and inducible nitric oxide synthase (iNOS) genes were in line with the ELISA results." (PMID 34195100, 2021). "Besides, the number of splenic IL-6 secreting Transitional T2 B cell and T3 B cell were elevated in the splenocytes of antimony-drug resistant SbR-BHU138 strain infection." (PMID 34209841, 2021). "There is an early spike in IL6 transcription in early infection, which is not so apparent in later stages." (PMID 34775962, 2021). "Based on these cytokine data, we conclude that the flame burn produces an initial short-lived IL-6 response from the viable tissue adjacent to the burn site that is transient in the absence of an infection." (PMID 34152806, 2021). "Our previous study showed that IL‐6 and TNF‐α levels in the bronchoalveolar lavage fluid of A(H1N1)pdm09‐infected mice were significantly higher than those in seasonal H1N1‐infected mice within 3 days after infection." (PMID 33470564, 2021). "At day 2 post‐infection, the levels of IL‐6 and IL‐8 were significantly increased in the absence of PBMCs." (PMID 33173719, 2021). "Infection led to increases in proinflammatory CCL2, IFNγ, IL6 and CXCL10 in wt mice." (PMID 34237114, 2021). "The lower expression of E-cadherin in O. viverrini infection alone may be due to interleukin 6 (IL-6) and TGF- β1 production during infection." (PMID 34578122, 2021). "In the context of infection, the B. abortus T4SS effector virB-coregulated effector C (VceC) induces ER stress through interaction with the chaperon BiP and triggers NOD1/2- and RIP2-dependent IL6 production." (PMID 34201509, 2021). "The host response to infection could be regulated by TGFβ1 with the help of a cytokine storm and the presence of TNF, IL-1β, and IL-6." (PMID 33693030, 2021). "MFI of the TNF-α and IL-6-producing LKS+ cells was higher in the spleen than in the bone marrow of the PCA2-infected mice, indicating that in response to the secondary infection the splenic HSPCs are better prepared to produce proinflammatory cytokines." (PMID 34975887, 2021). "This in turn eludes to why such a series of triggers could lead to IL-6 and TNF-α production, dissemination of the infection and culminate in pathological situations as observed in MCL." (PMID 33765083, 2021). "Additionally, IL-6 is critical for differentiation and maintenance of IL-23 dependent TH17 cells- important for recruitment of neutrophils to infection site, and IFNγ mediated control of M tuberculosis." (PMID 33995365, 2021).
infection (continued). "Comparing levels of cytokines at the acute and convalescent phases, we found that concentrations of IL-1ra, IL-6, IL-18, and MCP-1 were relatively higher during the acute phase of infection, suggesting that these cytokines potentially play key roles in controlling O. tsutsugamushi infection." (PMID 34451491, 2021). "For the validation of the data obtained for gene expression after infection with the NmB and NmC strains in presence and absence of the capsule, il6, il8, nfkbiz, zc3h12a and tnf were chosen." (PMID 34863201, 2021). "In the absence of IL-6 or the IL-6 receptors, mice were reported to perish after infection with a sublethal dose of H1N1." (PMID 34684240, 2021). "The pro-inflammatory cytokines, e.g., IL-6, TNF-α, and IL-1β, involved in the pathological processes of rejection and infection in baboon xenograft recipients, and may be associated with coagulation dysfunction." (PMID 34956220, 2021). "Unlike the lung, however, the frequency of IL-6+ cells in the spleen was only affected by age, with no infection-inducing effects observed." (PMID 34471088, 2021). "In addition, we found that systemic IL-6 and IL-10 levels in patients with an SFTSV infection more strongly correlated with outcomes (for severe disease with an ultimate outcome of recovery or death) than did viral load and neutralizing antibodies." (PMID 34484214, 2021). "Along with this observation, we also observed significantly lower levels of IL-6, IFN-γ, and CXCL-10 24 h post-infection, IL-17A and TNF-α 4 days post-infection, and IL-1β, CCL2 and CCL5 7 days post-infection in the lung of IL-38-treated mice, compared with mice without IL-38 administration." (PMID 33414457, 2021). "Both TNF-α and IL-6 are critical proinflammatory cytokines against pathogen infection, and a lack of TNF-α and IL-6 results in higher mortality and more susceptibility to bacterial infection." (PMID 34564598, 2021). "Likewise, we saw a significant increase in the levels of IL-6 in the plasma of M. tb-infected mice treated with DEM at 2 weeks, 4 weeks, and 8 weeks post-infection compared to the sham group." (PMID 35371562, 2021). "IL-6, IL-23, and TGF-β and were seen in reduced levels at least in one post-infection period after L-Kyn and CH223191 treatments and this was accompanied by reduced levels of IL-17 (week 2) and IL-22 (both infection periods)." (PMID 33936043, 2021). "We could show that levels of IL-6 and CRP are significantly higher in trauma patients who develop post-traumatic infection." (PMID 34568354, 2021). "At the same time, they found that serum ESR, CRP, and interleukin 6 (IL-6) had no benefits in predicting infection persistency before second-stage prosthesis implantation." (PMID 33774699, 2021). "Infection with SARS-CoV-2 influenced neither the effect of most TLR ligands- (upper row) nor VSV- nor Sendai Virus (SeV)-induced (middle row) IL-6 production by all cell types tested." (PMID 34122407, 2021). "Taken together, these results suggest that increased AF cytokines such as IL-6 and IL-8 are not necessarily a predictive signature of preterm labor, particularly during infection with the immunosuppressive hyaluronidase-expressing GBS bacteria." (PMID 33402537, 2021). "Our data showed that the levels of IL-6, IL-8, and TNF-α secreted by macrophages significantly increased after infection with C. glabrata, although they were lower than those reported for C. albicans infection, which is in consistence to report in previous work." (PMID 33680221, 2021). "In an otitis media model of infection with non-typeable Haemophilus influenzae, SP-A was shown to modulate the expression of pro-inflammatory markers, IL-6 and IL-1β, and these peaked at higher levels in SP-A KO mice." (PMID 35071140, 2021). "Furthermore, the IL-6 mRNA expression level in the lungs of groups IV and III were lower (p < 0.05) compared with group I at days 5 and 7 post-infection." (PMID 34988139, 2021).
infection (continued). "Furthermore, infection of ECSIT+/+ and WT BMDMs with S. typhimurium showed comparable activation of NF-κB and MAPK pathways and induction of IL-6 and TNF-α." (PMID 34032637, 2021). "However, infection with USA300 did trigger increased production of cytokines and chemokines related to severity, including IFNy, GM-CSF, TNFa, IL-4, and IL-6." (PMID 33573328, 2021). "To demonstrate that the improved resistance of immunobiotic-treated Calu-3 2B4 cells against the infection with SARS-CoV-2 was related to an enhanced antiviral immune response, we also determined IFN-β, IL-6, and chemokines concentrations in the culture supernatants of challenged cells." (PMID 34578229, 2021). "Regardless of the infection site, infection with the purified FliC protein induced a significant increase in IL-6 release at 5 h (between 2760.97 pg/mL and 3562.12 pg/mL) compared to 3 h (2200.06 pg/mL and 2441.95 pg/mL)." (PMID 34835359, 2021). "Similarly, infection of BMDM with the Mtb Δami4 mutant resulted in significantly increased production of IL-1α, IL-6, and IL-12p40." (PMID 33980132, 2021). "mRNA monitoring showed that IL-6 was commonly expressed only in the late phase of infection and exclusively for ZEBOV (not for RESTV)." (PMID 33917562, 2021). "Interleukin 6 (IL-6), interleukin 10 (IL-10), and monocyte chemoattractant protein 1 (MCP-1) were induced by infection of both the wild type and complemented strains; however, they were present at significantly lower concentrations in the lungs of mice infected with the dnj1∆ mutant." (PMID 34566931, 2021). "On post-infection day 5 and 6, the level of IL-6 remained high in the oseltamivir treated groups, unlike the EBN treated groups where the levels of pro-inflammatory cytokines were well regulated." (PMID 34025406, 2021). "Infection with γHV-68 alone induced expression of multiple cytokines, including IL-27, IL-23, IL-12, IL-6, and IL-2, while stimulation with kyn alone failed to increase cytokine expression." (PMID 33491663, 2021). "Furthermore, PCT performed better in predicting AKI than some well-known infection biomarkers such as CRP and interleukin-6." (PMID 34199069, 2021). "Levels of IL-4, IL-5, and IL-6 were not significantly elevated in any infection group versus mock infection." (PMID 34202420, 2021). "This correlated with a decrease in inflammatory cytokine expression (Il1b, Tnf, and Il6) by DIO Mφs given IFNβ during MHV-A59 infection compared to infected DIO BMDMs not treated with IFNβ." (PMID 34479991, 2021). "Addition of IFNγ 1 h after establishment of infection still resulted in a dampening of the epithelial release of IL-8, but not IL-6." (PMID 34015044, 2021). "In contrast, the only cytokine detected in mice that received a burn without infection was IL-6, which peaked at 24 h and returned to baseline levels after 48 h." (PMID 34152806, 2021). "In conclusion, this study indicates that at the initial stage of SARS-CoV-2 and SFTS infection, the blood indices of patients are distinct from each other, including WBC count, absolute LYMPH count, PLT count, absolute CD4+ T cells count, and IL-6, TNF-α, D-D, CRP and FIB levels." (PMID 34238962, 2021). "We found that infection of SARS-CoV-2 could elevate the expression of Tnfα and Il-6, and downregulate the expression of Glut1, and these effects were blocked by the knockdown of REST." (PMID 34916489, 2021). "Moreover, 12 patients transferring to the ICU had higher concentrations of infection-related biomarkers (ESR, IL2R, IL6, IP10, PCT, SF, CRP, TNFα)." (PMID 33542448, 2021). "Although blunted overall, there was an early significant increase in IP-10, a chemoattractant for monocytes, T cells, and NK cells, and trends, albeit not significant, for elevated IL-6, IL-17, and KC in the early time points (days 1–3) post-infection." (PMID 33376758, 2021).
infection (continued). "Comparison of cytokine levels in the BAL of CF children with or without P. aeruginosa infection to healthy controls showed increased IL-6 levels regardless of infection status, and increased IL-5 concentration, which was further enhanced during infection." (PMID 33478382, 2021). "In contrast, in the infected control group, IL-2, IL-4, IL-6, and IL-17a levels rose slowly and did not change significantly after day 21 post-infection." (PMID 33717108, 2021). "Likewise, IL-6 expression was induced after infection, and fish that received SSWE had higher transcript levels of IL-6 in the HK." (PMID 35140710, 2021). "(C) The level of IL-12/23 p40 and IL-10 didn’t change with the change of intracellular CFU (P<0.05), while the level of TNF-α and IL-6 increased with the intracellular CFU decreasing, and the increase level of TNF-α was lower than that of the infection group (P<0.05)." (PMID 35003120, 2021). "An increase in IL-6 production by fetal membranes and other feto-maternal tissues in response to infection is likely a non-specific innate response and not an indication of a functional mediator of any labor-inducing pathways." (PMID 32848846, 2020). "On Day 0 (day of infection), we were not able to detect IL‐6 or IL‐11 in the supernatants of all 3D cultures (infection and negative control)." (PMID 32588533, 2020). "Infection resulted in immune-cell activation, with upregulation of cell surface activation markers (e.g., CD80, PD-L1, HLA-DR) and secretion of proinflammatory cytokines (IFN-α2a, IL-6, IL-8, TNF-α)." (PMID 32088771, 2020). "These variations in the median concentrations of IL-6 and CRP among neonates infected by different microorganisms might be due to the difference in the host inflammatory response during infection by different microorganisms." (PMID 33233806, 2020). "In addition, I3C treatment reduced the inflammatory response to Cr infection by maintaining anti-inflammatory cytokine IL-22 mRNA levels while reducing expression of other pro-inflammatory cytokines including IL17A, IL6, IL1β, TNF-α, and IFN-γ." (PMID 33076301, 2020). "Consistent with results regarding immune cell and neutrophil numbers, the concentrations of IL-1α, IL-6, and IL-12 subunit p40 in BALF on day 1 post-Mp infection were significantly lower or tended to be lower in C57BL/6J, DBA/1, and CBA/N mice than in BALB/c mice." (PMID 33520736, 2020). "TNF-α, IL-6, CXCL10, and IFN-β were induced after infection with all three viruses." (PMID 32849329, 2020). "Pro-inflammatory factor IL-6 did not decline within 60 h after infection, while IL-8 expressions peaked at 48 h." (PMID 31947624, 2020). "For teleosts, which rely on non-specific immune processes to enhance their immune response and resist pathogen infection, cytokines such as TNF-α, IL-1β, IL-6, IL-10, IL-12, and TGF-β, primarily produced by activated macrophages, also play an important role in the immune system." (PMID 32457762, 2020). "Various inflammatory cytokines (IL-1β, IL-6, IL-12, TNF-α) are increased inleptospirosis as an immune response to the infection, however, this increase may behigher in severe stages of the disease." (PMID 32578717, 2020). "Additionally, in vitro infection of human monocytes with SARS-CoV-2 leads to the production of several inflammatory cytokines, such as IL-6, IL-1β, TNF-α, and IFN-I." (PMID 33193377, 2020). "In terms of IL-6, the significant differences could be found between HD virus (HMC-1 cells) group and HD virus (A549 cells) (P < 0.01) at day 6 post-infection." (PMID 33304349, 2020). "In detail, out of 471 neonates with no clinical signs of infection within 72 h, 139 neonates showed IL-6 greater 11 pg/ml." (PMID 32793528, 2020). "We measured TNF-α, IL-6, IFN-γ, IL-17A and IL-10 after an experimental intravenous infection with S. suis serotype 2 in vivo, and analyzed whole blood, peripheral blood mononuclear cells (PBMC) and separated leukocytes to identify the cytokine-producing cell type(s)." (PMID 31947746, 2020).